ADRB1 (adrenoceptor beta 1)
Description:
G protein-coupled receptor for catecholamines that couples to G(s) proteins to activate adenylate cyclase and cAMP-dependent pathway. Binds epinephrine and norepinephrine with approximately equal affinity. Mediates the activation of Ras via binding with cAMP-dependent RAPGEF2. As part of the sympathetic nervous system, plays a role in the physiologic regulation of cardiac functions such as stimulation of cardiomyocyte contraction. Also delivers proapoptotic signals in cardiomyocytes (By similarity). Involved in the regulation of sleep/wake behaviors.
Synonyms: ADRB1R; B1AR; BETA1AR; FNSS2; RHR
Tractability: Small molecule: an approved drug acts on it; a structure with a bound ligand is known; a high-quality ligand is known; it belongs to a druggable protein family. Antibody: its Gene Ontology location is reachable by antibodies, with high confidence; UniProt places it where antibodies can reach, with medium confidence; UniProt predicts a signal peptide or a membrane-spanning region. PROTAC: a small molecule that binds it is known.
Target class: Small molecule receptor (family A GPCR); Adrenergic receptor; Monoamine receptor; Membrane receptor; Family A G protein-coupled receptor
Chemical probes: CHEMBL200234
Safety:
Unwanted effects reported when the protein is acted on. In parentheses: how it was acted on, where the effect was seen, and who reports it.
increased heart rate (Urban et al. (2012): activation, cardiovascular system; Lynch et al. (2017): activation, acute dosing, cardiovascular; Bowes et al. (2012): activation, cardiovascular system, gastrointestinal)
decreased blood pressure (Bowes et al. (2012): inhibition, cardiovascular system, gastrointestinal; Lynch et al. (2017): inhibition, acute dosing, cardiovascular)
decreased heart rate (Lynch et al. (2017): inhibition, acute dosing, cardiovascular; Bowes et al. (2012): inhibition, cardiovascular system, gastrointestinal)
increased cardiac contractility (Bowes et al. (2012): activation, cardiovascular system, gastrointestinal; Lynch et al. (2017): activation, acute dosing, cardiovascular)
bradycardia (inhibition; cardiovascular system; source: Urban et al. (2012))
bronchospasm (activation, acute dosing; cardiovascular; source: Lynch et al. (2017))
cardiac hypertrophy (activation, chronic dosing; cardiovascular; source: Lynch et al. (2017))
cardiac muscle stimulation (activation; cardiovascular system; source: Urban et al. (2012))
cardiovascular performance (inhibition; cardiovascular system; source: Urban et al. (2012))
decreased cardiac output (inhibition; cardiovascular system, gastrointestinal; source: Bowes et al. (2012))
electrolyte disturbances (activation; cardiovascular system, gastrointestinal; source: Bowes et al. (2012))
heart failure (activation, chronic dosing; cardiovascular; source: Lynch et al. (2017))
increased force of contraction (activation; cardiovascular system; source: Urban et al. (2012))
increased renin release (activation; cardiovascular system, gastrointestinal; source: Bowes et al. (2012))
lipolysis (activation; cardiovascular system, gastrointestinal; source: Bowes et al. (2012))
myocardial fibrosis (activation, chronic dosing; cardiovascular; source: Lynch et al. (2017))
relaxation of blood vessels (activation; cardiovascular system; source: Urban et al. (2012))
relaxation of colon and oesophagus (activation; cardiovascular system, gastrointestinal; source: Bowes et al. (2012))
ventricular fibrillation (activation, acute dosing; cardiovascular; source: Lynch et al. (2017))
edema (source: ClinPGx)
major adverse cardiac events (mace) (source: ClinPGx)
Gene: Protein-coding gene on chromosome 10 (114,043,866 to 114,046,904, forward strand). Ensembl gene ENSG00000043591.
Subcellular location: Cell membrane
Pathways (Reactome):
Signal Transduction: Adrenoceptors; G alpha (s) signalling events
Gene Ontology:
Molecular function: alpha-2A adrenergic receptor binding; beta1-adrenergic receptor activity; PDZ domain binding; protein binding; protein heterodimerization activity; beta-adrenergic receptor activity; adrenergic receptor activity; G protein-coupled neurotransmitter receptor activity; G protein-coupled receptor activity
Biological process: adenylate cyclase-activating adrenergic receptor signaling pathway; positive regulation of heart rate by epinephrine-norepinephrine; regulation of circadian sleep/wake cycle, sleep; adenylate cyclase-activating G protein-coupled receptor signaling pathway; norepinephrine-epinephrine-mediated vasodilation involved in regulation of systemic arterial blood pressure; positive regulation of cardiac muscle cell apoptotic process; positive regulation of cold-induced thermogenesis; positive regulation of MAPK cascade; G protein-coupled receptor signaling pathway; positive regulation of heart contraction
Cellular component: early endosome; plasma membrane; membrane; neuronal dense core vesicle; Schaffer collateral - CA1 synapse
Genetic constraint (gnomAD): Loss-of-function variants: 1 observed, 0.27 expected, observed/expected ratio (o/e) 3.64. That is too few expected variants to judge how well the gene tolerates losing a copy. Missense variants: 592 observed, 538.11 expected, observed/expected ratio (o/e) 1.1, 90% interval 1.03 to 1.18. Synonymous variants: 340 observed, 269.16 expected, observed/expected ratio (o/e) 1.26, 90% interval 1.15 to 1.38.
Homologues: Orthologues: chimpanzee ADRB1 (99% identical), macaque ADRB1 (98% identical), mouse Adrb1 (90% identical), rat Adrb1 (90% identical), pig ADRB1 (89% identical), guinea pig ADRB1 (84% identical), tropical clawed frog adrb1l (52% identical), zebrafish adrb1 (50% identical), Caenorhabditis elegans ser-5 (23% identical). Paralogues in human: ADRB2 (44% identical), ADRB3 (41% identical), ADRA1D (29% identical), ADRA1B (29% identical), ADRA1A (27% identical), ADRA2A (25% identical), ADRA2B (23% identical), ADRA2C (23% identical), DRD2 (22% identical), GPR101 (19% identical), OR56A4 (12% identical), OR56A1 (12% identical), and 6 more.
Diseases named in the same sentence as ADRB1 in open-access papers:
ADRB1 is named in the same sentence as 157 diseases in open-access papers, as found by Europe PMC text mining. Sharing a sentence is not in itself a finding about the gene and the disease. The quoted sentences say what the papers report.
heart failure (75 papers, 2008 to 2026). Inability of the heart to pump blood at an adequate rate to meet tissue metabolic requirements. "A recent study assessed the role of ADRB1 (1165G > C) gene polymorphisms on BBs response in a population with heart failure, revealing that the patients with the CC genotype seemed to receive the most benefit from a high BBs dose." (PMID 38298191, 2024). "A few previous studies revealed that a mutation in ADRB1 (1165G > C) was associated with the survival of patients with heart failure by increasing the dose of BBs." (PMID 38298191, 2024). "The ADRB1 gene, which encodes for the beta-1 adrenergic receptor, is one of the genes that have an impact on the response of beta blockers which are commonly used in the treatment of heart failure and hypertension." (PMID 38420192, 2024). "Support for the influence of ADRB1 polymorphisms on response to beta-blockers is available in cases of heart failure and hypertension." (PMID 37753361, 2023). "ADRB1 is implicated in cognitive neural diseases, possibly due to its role in neuroinflammatory processes, and is also associated with heart failure." (PMID 32756008, 2020). "In total, three polymorphisms in the ADRA2C gene and five polymorphisms in the ADRB1 gene appear to be implicated in epistatic effects on heart failure survival." (PMID 18947427, 2008). "In this study, we identified multiple polymorphisms within the ADRA2C and ADRB1 genes that interact to increase risk of death or transplant in heart failure patients." (PMID 18947427, 2008). "Multiple polymorphisms act synergistically between the ADRA2C and ADRB1 genes to increase risk of death or cardiac transplant in heart failure patients." (PMID 18947427, 2008). "Although we did not observe intragenic epistatic interactions between the ADRA2C and ADRB1 genes, we did observe multiple polymorphisms acting synergistically between the ADRA2C and ADRB1 genes to increase risk of death or cardiac transplant in heart failure patients." (PMID 18947427, 2008). "While GRK2 is upregulated, several studies documented that the β1-adrenoceptor (ADRB1) is downregulated in human heart failure." (PMID 35203304, 2022). "For example, we found a highly significant down-regulation of the beta 1 adrenergic receptor (ADRB1) in 19/21 groups, which is well known for its crucial role in heart function and down-regulation in heart failure." (PMID 24289243, 2013). "The purpose of this study was to investigate possible synergistic effects of polymorphisms of these two intronless genes (ADRB1 and ADRA2C, respectively) on the risk of death/transplant in heart failure patients." (PMID 18947427, 2008). "Lower abundance of Adrb1 transcript is also commonly found in patients with heart failure." (PMID 39761962, 2025). "In cardiovascular diseases such as heart failure, β-adrenergic receptor downregulation and desensitization may attenuate the expected effects of ADRB1 and ADRB2 genetic variation on β-blocker response." (PMID 40283930, 2025). "MYH6 and ADRB1 down-regulation are key components of contractile dysfunction in heart failure." (PMID 31687497, 2019). "Besides, considering that ADRB1 and ADRB2 play an essential role in heart failure, ADRB1 and ADRB2 were used as a control to validate the effect of QLQX." (PMID 31619994, 2019). "Given the potential synergistic effects of these polymorphisms in the ADRB1 and ADRA2C genes, two previous studies have investigated and identified epistatic interactions affecting heart failure risk and response to β-blockers in heart failure patients." (PMID 18947427, 2008). "Evidence has shown that a reduction in the ADRB1/ADRB2 ratio has been observed in heart failure, and the use of adrenoceptor beta blockers is a cornerstone of current heart failure therapy." (PMID 31619994, 2019).
heart failure (continued). "Here we examine whether there is evidence for more complex intragenic and intergenic epistatic effects on heart failure phenotypes and survival in these genes utilizing 16 DNA sequence variations in the ADRA2C and 17 DNA sequence variations in the ADRB1 genes." (PMID 18947427, 2008).
Hypertension (35 papers, 2010 to 2025). The presence of chronic increased pressure in the systemic arterial system. "Studies had established that ADRB1 (1165G > C) dominant allele C was a risk factor for hypertension." (PMID 38298191, 2024). "As sotalol and amosulalol both directly block ADRB1, a protein and gene associated with hypertension, and amosulalol has anti-hypertensive effects, it is reasonable that sotalol also has anti-hypertensive effects." (PMID 39149283, 2024). "Several genetic association studies revealed that the Arg allele of the ADRB1 rs1801253 is related to hypertension risk, but the Gly allele confers a decreased risk in Asian and Chinese populations." (PMID 38935682, 2024). "Among them, ADRB1 R389G has been reported to be associated with chronic diseases related to obesity such as high blood pressure, atherosclerosis, and fatty liver." (PMID 32397206, 2020). "A previous study summarized the pharmacogenomics of hypertension treatment, and the most common genetic variants involved in the metabolism of the five classes of drugs included ADRB1 (1165G > C), CYP2D6∗10, CYP2C9∗3, AGTR1 (1166A > C), ACE (I/D), CYP3A5∗3, and NPPA (2238T > C)." (PMID 38298191, 2024). "The mutation rate of the ADRB1 (1165G > C) gene (74.43%) was slightly higher than that in Chinese patients with essential hypertension reported previously (59.8%), while the mutation rate of CYP3A5∗3 (69.58%) was slightly lower than that reported previously (79.5%)." (PMID 38298191, 2024). "ADRB1 is important in the regulation of blood pressure, cardiovascular function and lipid metabolism, and it was found that individuals with higher expression of the ADRB1 receptor gene are at increased risk of hypertension." (PMID 35933330, 2022). "In addition, the c.971_982del of rs61767072 of the adrenoceptor-α2 (ADRA2) gene was associated with CIs when patients had hypertension and hyperhomocysteinemia, and the c.145A>G (rs1801252) polymorphism of the ADRB1 gene was associated with small artery occlusion." (PMID 33352859, 2020). "Haplotype analysis of ADRB1, PTRD, TCF7L2 gene variants among hypertension patients and healthy controls." (PMID 38935682, 2024). "For example, the pathway identified by our approach in the between sotalol hydrochloride and hypertension, traverses through ADRB1, a commonly shared target by amosulalol and sotalol, in order to treat hypertension." (PMID 39149283, 2024). "In the gene expression signature for hypertension, ADRB1 and ACE were both upregulated, as expected." (PMID 35013250, 2022). "For instance, ADRB1 and ADRA2A genes linked the four most common cardiometabolic disorders (coronary diseases, hypertension, diabetes, obesity) with BPD and depressive disorder." (PMID 28117839, 2017). "A canonical avenue sotalol may manage hypertension is through inhibition of ADRB1, a β-adrenergic receptors." (PMID 39149283, 2024). "Utilizing our computational repurposing approach, we propose three mechanisms by which sotalol may moderate hypertension (a condition characterized by increased arterial blood pressure) through potassium channel activity, ADRB1 and FNDC4." (PMID 39149283, 2024). "ADRB1 and ADRB2 were targeted by drugs from all the four groups, and activation and inhibition of beta-adrenoreceptors caused opposite effects on asthma and hypertension." (PMID 31705029, 2019). "In contrast, for the autonomic dysfunction phenotype, brainstem Il1b and kidney Adrb1 dynamics showed increases during the pre-hypertensive and hypertension-onset time frames, respectively, which could be related to the absence of Ren-mediated influence." (PMID 28732007, 2017). "In 2018, the GWAS catalog found seven candidate genes with an established pathophysiological role in hypertension, namely ACE1, ACE2, ADRB1, ADRB2, MME, CACNA2D2, and UMOD." (PMID 36902588, 2023). "As a secondary analysis, we also hypothesized that genetic variation in ADRB1, CYP3A5, and NEDD4L genes may explain BP variation in hypertension." (PMID 39063918, 2024).
myocardial infarction (25 papers, 2008 to 2025). Gross necrosis of the myocardium, as a result of interruption of the blood supply to the area, as in coronary thrombosis. "Patients with the ADRB1 Gly389 polymorphism were at higher risk for the composite outcome due to higher rates of myocardial infarction (adjusted hazard ratio [HR] 3.63, 95% confidence interval [95%CI] 1.17–11.28; Gly/Gly vs. Arg/Arg HR 4.14, 95%CI 0.88–19.6)." (PMID 18331634, 2008). "The β1-adrenergic-receptor (ADRB1) antagonist metoprolol reduces infarct size in acute myocardial infarction (AMI) patients." (PMID 28416795, 2017).
dilated cardiomyopathy (19 papers, 2012 to 2025). Cardiomyopathy which is characterized by dilation and contractile dysfunction of the left and right ventricles. "In order to provide firm evidence that changes in mRNA expression associated with LV RR in BB-treated patients with dilated cardiomyopathy were from genes regulated by β1-AR signaling, we used ADRB1 Arg389 and Gly389 cardiac overexpressor Tg mice as a biologic filter." (PMID 37606047, 2023). "Autoantibodies to ADRB1 isolated from the blood of patients with dilated cardiomyopathy stimulated the proliferation of T cells isolated from rat blood." (PMID 40869214, 2025). "Gene Set Enrichment Analysis (GSEA) performed with TCGA data indicated that the calcium signaling pathway, dilated cardiomyopathy, endocytosis, and neuroactive ligand-receptor interactions were significantly enriched in samples with ADRB1." (PMID 33234738, 2020). "Interestingly, ADRB1, the β − 1-adrenergic receptor was the second highest impact gene for dilated cardiomyopathy, which is often treated with beta-blockers targeting the adrenergic receptor." (PMID 31479446, 2019).
Obesity (19 papers, 2006 to 2025). Accumulation of substantial excess body fat. "In some populations, obesity and body weight related disorders show a correlation with polymorphisms in three subtypes of beta-adrenoceptor (β1, β2, and β3) [ADRB1, ADRB2 and ADRB3] genes." (PMID 29587766, 2018). "In 2008, Ohshiro and coworkers had shown a strong association between mutations in the ADRB1 and massive obesity in Japanese." (PMID 29587766, 2018). "For example, two single nucleotide polymorphisms (SNPs) of ADRB2 (Gly16Arg and Gln27Glu) and one of ADRB1 (Gly389Arg) were associated with obesity and T2DM in a Swedish and a Finnish study." (PMID 17150099, 2006). "ADRB2 (Gly16Arg and Gln27Glu) and ADRB1 (Gly389Arg) have both been shown to be associated with obesity and T2DM." (PMID 17150099, 2006). "Since in our previous report, we had observed an association between Gln27Glu polymorphism of ADRB2 gene, obesity, and other related disorders in Saudi population our interest was to explore if any association existed between ADRB1 (rs1801253) and ADRB3 (rs4994) and these abnormalities." (PMID 29587766, 2018). "Genes implicated in monogenic obesity include POMC, LEP, LEPR, MC3R, and MC4R, while polygenic obesity involves variants in genes such as FTO, UCP1-3, MC4R, ADRB1-3, and SLC6A14." (PMID 41302083, 2025). "In male offspring, associated dmCpGs were linked to known obesity-related genes including B4GALNT4 (cg25020933, cg15762098), ADCY9 (insulin secretion and thyroid hormone synthesis) (cg00610508), ADRB1 (cg13848598) and ATP10D (cg14009629)." (PMID 40410506, 2025). "Polymorphisms in the three subtypes of β-adrenoceptor (ADRB1, ADRB2, and ADRB3 genes) show a correlation with obesity and body weight-related disorders." (PMID 33113859, 2020). "We scanned for the polymorphism of Arg389Gly (rs1801253) in ADRB1 and Trp64Arg (rs4994) in ADRB3 genes in Saudi population to determine association, if any, of these polymorphisms with obesity and related disorders." (PMID 29587766, 2018). "The ADRB1 is a candidate gene for obesity due to its role in catecholamine mediated energy homeostasis." (PMID 29587766, 2018). "This is the first study to report the relationship between ADRB1 and ADRB3 gene polymorphism and obesity-related phenotypes in the Saudi population." (PMID 29587766, 2018). "In addition, p-synephrine was predicted to exert its anti-obesity effect via calcium and cAMP signaling pathways by targeting adrenergic receptors, ADRB1, ADRB2, and ADRB3." (PMID 34944408, 2021). "A few SNPS had p-values suggestive of associations, including one obesity-related SNP, [rs2815752 (NEGR1), unadjusted p = 0.004] and several HTN-related SNPs [rs13139571 (GUCY1A3-GUCY1B3), rs11191548 (CYP17A1-NT5C2) and rs1801253 (ADRB1), each with unadjusted p = 0.01]." (PMID 31141530, 2019). "In fact, our findings for Arg389 Gly polymorphism in ADRB1 amongst Saudi population are in line with earlier published reports and suggest that ADRB1 Arg389Gly polymorphisms do not contribute to obesity and related disorders in the Saudi population." (PMID 29587766, 2018).
Arrhythmia (16 papers, 2014 to 2025). Any cardiac rhythm other than the normal sinus rhythm. "For example, VDR is proven to be with the function of regulating vasodilatation; ADRB1 (Beta-1 adrenergic receptor) and ADRB2 (Beta-2 adrenergic receptor) serve as the vital role in the pathology and biology process of arrhythmia." (PMID 29321678, 2018).